FHL1 (four and a half LIM domains 1)
Diseases named in the same sentence as FHL1 in open-access papers (continued):
Sharing a sentence is not in itself a finding about the gene and the disease.
myositis (4 papers, 2018 to 2025). "Anti-FHL1 autoantibody levels correlated with CK (r = 0.62, P= 0.01), disease activity measured using the Myositis Disease Activity Assessment Tool (MYOACT) (n = 14, P = 0.004) and inversely with Manual Muscle Test-8 (r = −0.59, P = 0.02) at baseline." (PMID 38833674, 2025). "A number of antibodies are also linked to an increased risk of dysphagia: NXP2, FHL-1, SAE, HMGCR, NT5c1A, SRP, TIF1y, OJ and myositis-specific or -associated autoantibodies in general." (PMID 32650400, 2020). "Furthermore, granzyme B cleavage sites have been identified in autoantigens, such as FHL1 and HisRS, targeted in autoimmune disorders, including myositis." (PMID 30157932, 2018). "In a subgroup, repeated measurements of the six-item core set measures for evaluation of myositis disease activity were available at baseline for 12 anti-FHL1+ and 6 FHL-; and after 3–5 years for 15 anti-FHL1+ and 9 FHL1− patients with IIM." (PMID 38833674, 2025). "We generated FHL1−/− mice, which when infected with CHIKV or o’nyong-nyong virus (ONNV) displayed reduced arthritis and myositis, fewer immune infiltrates, and reduced proinflammatory cytokine/chemokine outputs, compared to infected wild-type (WT) mice." (PMID 37884534, 2023). "Here, the authors use a FHL1−/− knockout mouse model to show that the FHL1 splice variant impacts arthritis and myositis after chikungunya or o’nyong-nyong infections but not Ross River or mayaro virus infection." (PMID 37884534, 2023).
non-small cell lung carcinoma (4 papers, 2017 to 2025). A group of at least three distinct histological types of lung cancer, including non-small cell squamous cell carcinoma, adenocarcinoma, and large cell carcinoma. "Conversely, OTUD1 and OTUD5 deubiquitinated and stabilized KLF4, FHL1, and PTEN, respectively, which effectively suppressed the progression of non-small cell lung cancer (NSCLC)." (PMID 40469292, 2025).
thyroid cancer (4 papers, 2011 to 2025). "Furthermore, Four and a half LIM domains protein 1 (FHL1), which is a tumor suppressor gene in thyroid cancer, was downregulated in FTC." (PMID 40740986, 2025). "Some proteins' alteration was found in thyroid cancer, such as CK19, TG, Ki67, Calcitonin, TTF-1, BRAF, RET, HBME-1, SERPINA1, TfR1/CD71, FHL1 and galectin-3." (PMID 22188859, 2011).
acute promyelocytic leukemia (3 papers, 2020 to 2025). An aggressive form of acute myeloid leukemia (AML), characterized by arrest of leukocyte differentiation at the promyelocyte stage, due to a specific chromosomal translocation t(15;17) in myeloid cells. "Moreover, RHOBTB2 expression was increased in non-acute promyelocytic leukemia (APL) subtypes, patients without FLT3 mutation and PML/RAR fusion, and imparted a positive correlation with the expression of FLT3, FHL1, and RUNXs." (PMID 34074803, 2021).
Atrophy (3 papers, 2016 to 2019). Any weakening or degeneration, especially through lack of use. "FHL1‐associated myopathies might result in muscular atrophy or hypertrophy with a pseudoathletic phenotype." (PMID 31293105, 2019). "It seems reasonable to assume that the detection of diglycine modification sites on obscurin and FHL1 indicates that these M-band proteins are degraded by the E3 ubiquitin ligase MURF1 and TRIM32 during early atrophy." (PMID 28546288, 2017).
colon carcinoma (3 papers, 2014 to 2021). "We further evaluated this relationship by overexpressing or knocking down FHL1 in colon cancer cells." (PMID 34335951, 2021). "On the other hand, the downregulation of FHL1 has been detected in multiple gastric and colon cancer, and the silencing of FHL1 promoted cell growth, migration, and invasion in gastrointestinal cancer cells." (PMID 33322515, 2020). "To explore the possibility that miR-410 may regulate the methylation status of the FHL1 gene, we prepared HepG2 liver cells and LS180 colon carcinoma cells over-expressing either miR-410 or control oligonucleotides." (PMID 25272045, 2014).
Fabry disease (3 papers, 2022 to 2024). Fabry disease (FD) is a progressive, inherited, multisystemic lysosomal storage disease characterized by specific neurological, cutaneous, renal, cardiovascular, cochleo-vestibular and cerebrovascular manifestations. "We have also identified P/LP variants in HCM phenocopy genes such as GLA related to Fabry disease and FHL1 related to X-linked muscular dystrophy." (PMID 37178278, 2023).
head and neck squamous cell carcinoma (3 papers, 2016 to 2023). A squamous cell carcinoma that arises from any of the following anatomic sites: lip and oral cavity, nasal cavity, paranasal sinuses, pharynx, larynx, and salivary glands. "Using bioinformatics and Venn analysis of gene transcriptional profiling, we identified downregulation of X-linked four-and-a-half LIM domains protein 1 (FHL1) gene in head and neck squamous cell carcinoma (HNSCC)." (PMID 26908444, 2016). "Moreover, the knockdown of FHL1 enhanced tumorigenesis in vivo and in vitro, which suggests that this protein could be a therapeutic target for treating head and neck squamous cell carcinoma." (PMID 36752296, 2023).
lymph node metastasis (3 papers, 2016 to 2021). "Positive FHL1 expression was significantly correlated with differentiation, lower lymph node metastasis, early T stage, and clinical stage." (PMID 32587768, 2020). "Multivariate Cox analysis showed that FHL1 expression (p = 0.021; HR 0.404, Cl, 0.187–0.871) together with lymph node metastasis (p = 0.017; HR 2.334, Cl, 1.167–4.671) was verified as independent predictors of OS and DFS in patients with HNSCC." (PMID 26908444, 2016).
ovarian tumour (3 papers, 2002 to 2008). "The immunohistochemical evidence of tumour-associated factor H/FHL-1 suggested that the ovarian tumour cells could carry surface components that bind factor H and/or FHL-1, proteins which both have binding sites for glycosaminoglycans and other polyanions." (PMID 12402151, 2002). "The secretion of both soluble C regulators, like FH/FHL-1, and the release of membrane regulators can thus provide additional resistance to ovarian tumours in the AF or at least restrict the activity of the C system within the AF." (PMID 15726105, 2005). "Together with the data obtained from the immunoblotting and ELISA analyses of ascites samples the immunohistochemical observations suggested that ovarian tumour cells are capable of producing FHL-1 and factor H into their microenvironment." (PMID 12402151, 2002). "SK-OV-3, Caov-3, PA-1 and SW626 ovarian tumour cells were found to bind both 125I-labelled factor H and FHL-1 to their cell surfaces." (PMID 12402151, 2002). "In this study, we observed that ovarian tumour cells can secrete and/or utilise functionally active inhibitors of the cytolytic C system, factor H and FHL-1." (PMID 12402151, 2002). "As the patients (n=16) from whom the samples were obtained had different types of ovarian tumours and samples from all of them were positive for FHL-1 it is likely that the production of FHL-1 is a general feature of ovarian tumours." (PMID 12402151, 2002). "In addition, FH and FHL-1 are abundantly present in ovarian carcinoma ascites and primary tumors, and ovarian tumor cells have been reported to bind both FH and FHL-1 and to promote factor I-mediated cleavage of C3b to inactive iC3b." (PMID 18652693, 2008). "Furthermore, FH and FHL-1 were found to be produced by ovarian tumour cells, and in solid ovarian tumours FH and FHL-1 were present in the apical tumour cell layers." (PMID 15726105, 2005). "We have observed that it is specifically the concentration of FHL-1 that is high in AF, and that functionally active FH and FHL-1 molecules are synthesised by the ovarian tumour cells." (PMID 15726105, 2005). "To investigate the presence of FHL-1 and factor H in ovarian tumours in vivo, we analysed cryostat sections of serous ovarian tumours with the VIG8 (detects SCR19-20 of factor H) and 196X (detects SCR1 of factor H and FHL-1) mAbs and immunoperoxidase staining." (PMID 12402151, 2002). "When the ovarian tumour cells were analysed by RT–PCR the SK-OV-3 and Caov-3 cell lines were found to express factor H and FHL-1 mRNAs, although the amount of FHL-1 mRNA was relatively low in the Caov-3 cells." (PMID 12402151, 2002). "RT–PCR and immunoblotting experiments showed that the SK-OV-3 and Caov-3, but not the PA-1 and SW626, ovarian tumour cell lines produced factor H and FHL-1 mRNA and protein." (PMID 12402151, 2002). "However, the current study is the first one to propose such a role for FHL-1 and to show the presence of FHL-1 in samples from patients with ovarian tumours." (PMID 12402151, 2002). "Two ovarian tumour cell lines that did not synthesize factor H or FHL-1 produced a soluble form of MCP/CD46 with a partially similar functional profile as factor H. Immunohistological analyses showed the presence of FHL-1 and factor H on ovarian tumours in vivo." (PMID 12402151, 2002).
tongue squamous cell carcinoma (3 papers, 2017 to 2023). A squamous cell carcinoma that arises from the tongue. "Another study showed that FHL1 inhibits growth of tongue squamous cell carcinoma cells by inducing G1/S cell cycle arrest, potentially through suppression of cyclin D and cyclin E expression." (PMID 32587768, 2020). "FHL1 has a tumor-suppressive role in tongue squamous cell carcinoma and accordingly may be a useful target for gene therapy." (PMID 28460433, 2017).
Arthritis (2 papers, 2022 to 2023). Inflammation of a joint. "In addition, since the expression of FHL1 is mainly found in skeletal muscle cells, the molecular interaction between nsP3 and FHL1 would influence the progression of arthritis in CHIKV-infected patients." (PMID 35401487, 2022).
cervical cancer (2 papers, 2017 to 2022). A primary or metastatic malignant neoplasm involving the cervix. "Endogenous FHL1 interacted with endogenous CDC25C, from both cytoplasmic and nuclear fractions of cervical cancer HeLa cells, in the absence or presence of IR." (PMID 28094252, 2017).
congenital myopathies (2 papers, 2017 to 2025). "In the congenital myopathy subgroup, 12 of 22 patients (54.5%) had disease-causing variants in RYR1 (n = 4), MYH7 (n = 3), TTN (n = 2), FHL1 (n = 1), NEB (n = 1), and SELENON (n = 1)." (PMID 40494860, 2025).
COVID-19 (2 papers, 2022). A disease caused by infection with severe acute respiratory syndrome coronavirus 2. "A study has shown that in COVID-19 patients, FHL1 is associated with the JAK–STAT pathway, which can indirectly activate STATs and induce various inflammatory responses." (PMID 36212830, 2022). "Because FHRs are closely related in terms of sequence – indeed FHL-1 is identical to the first third of FH with the exception of a unique 4 amino acid C-terminal tail – they have not been measured together previously in COVID-19 cohorts." (PMID 36330526, 2022).
Danon disease (2 papers, 2024). A lysosomal glycogen storage disease characterized by severe cardiomyopathy and variable degrees of muscle weakness, frequently associated with intellectual deficit. "Other diseases which can lead to an HCM phenotype include inflammatory diseases (e.g., sarcoidosis), storage diseases (e.g., Danon disease, hemochromatosis, PRKAG2), syndromal diseases (Friedreich ataxia, FHL‐1, malformation syndromes), mitochondrial diseases and drug-induced cardiomyopathy." (PMID 39352517, 2024).
glioma (2 papers, 2002 to 2017). A benign or malignant brain and spinal cord tumor that arises from glial cells (astrocytes, oligodendrocytes, ependymal cells). "When a total of 22 cell lines were tested only the ovarian cell lines SK-OV-3 and Caov-3, the glioma cell lines H2 and U138 and the K562 erythroleukaemia/lymphoblast cells constitutively produced factor H and FHL-1 to the culture medium." (PMID 12402151, 2002).
leukemia (2 papers, 2018 to 2020). A malignant (clonal) hematologic disorder, involving hematopoietic stem cells and characterized by the presence of primitive or atypical myeloid or lymphoid cells in the bone marrow and the blood. "Gene Set Enrichment Analysis performed to determine the biological functions related to FHL1 and potential molecular mechanisms showed enrichment of FHL1-related genes in leukemia stem cell (LSC) signatures, tumor-associated signaling pathways, and transmembrane transport of chemotherapeutic drugs." (PMID 32587768, 2020).
liver cancer (2 papers, 2020 to 2022). An epithelial or non-epithelial malignant neoplasm that arises from the liver. "FHL1 methylation is additionally involved in the associated mechanisms in human liver cancer." (PMID 32587768, 2020). "An investigation focusing on the regulation of FHL1 in hypoxia-inducible factor 1 (HIF-1) activity presented another potential mechanism through which FHL1 participates in liver cancer progression." (PMID 32587768, 2020). "A recent epigenetic analysis identified FHL1 as a tumor suppressor gene in human liver cancer and indicated that EZH2-imediated H3K27me3 is involved in epigenetic repression of FHL1 in HCC56." (PMID 32587768, 2020).
metastatic disease (2 papers, 2020 to 2025). "On the one hand, FHL1 expression is suppressed in several cancer types, which correlates with increased metastatic disease and decreased survival." (PMID 32587768, 2020).
muscle disorders (2 papers, 2012 to 2025). "However, in other muscle disorders like myofibrillar myopathies, inclusion body myopathies, nemalin myopathies, and FHL-1 mutation-associated muscle disorders protein misfolding has been implied." (PMID 23185377, 2012).
nemalin myopathies (2 papers, 2012 to 2017). "Differential accumulation of IAPs at MASs could impact on such congenital conditions as nemaline myopathy, which is caused by mutations in proteins constituting sarcomeric thin filaments, and myofibrillar myopathies caused by aggregation of proteins such as ZASP, filaminA and FHL1." (PMID 28446705, 2017).
oral squamous cell carcinoma (2 papers, 2018 to 2020). "Significant downregulation of FHL1 was demonstrated in all oral squamous cell carcinoma (OSCC)-derived cell lines and tissues from human patients, mediated by CpG hypermethylation of the FHL1 promoter region." (PMID 32587768, 2020).
ovarian carcinoma (2 papers, 2002 to 2008). A malignant neoplasm originating from the surface ovarian epithelium. "The abundant presence of factor H and FHL-1 in the AF samples and in the apical layers and extracellular matrix surrounding the tumour cells of patients with ovarian carcinoma suggest that C activation is controlled within the peritoneal cavity." (PMID 12402151, 2002). "The amounts of FHL-1 in ascites samples from ovarian cancer patients were found to be considerably higher than in NHS or in ascites from a patient with liver cirrhosis." (PMID 12402151, 2002). "The average FHL-1/factor H ratio in the ovarian cancer patient AF samples was found to be over three-fold higher than in NHS or in follicle fluids (17.5% vs 5.2% or 5.0%, respectively)." (PMID 12402151, 2002). "The current study was initiated by analysis of soluble C inhibitors factor H and FHL-1, the short truncated form of factor H, in ascites fluid (AF) samples of patients with ovarian cancer." (PMID 12402151, 2002). "Factor H and FHL-1 were also abundant in ascites fluid samples of patients with ovarian cancer." (PMID 12402151, 2002). "However, there were up to 3–4-fold differences in the amounts of factor H/FHL-1 between the AF samples of ovarian cancer patients." (PMID 12402151, 2002). "To further investigate the expression of FHL-1 and factor H in vivo we performed immunohistological analysis of tumour tissue samples obtained from 25 patients with serous cystadenocarcinoma, the most common type of malignant ovarian neoplasm." (PMID 12402151, 2002).
prostate carcinoma (2 papers, 2018 to 2019). A carcinoma that arises from epithelial cells of the prostate gland. "Notably, FHL1 as a tumor suppressor gene is reduced in the malignant cancers, including gastric 32, 33, breast, kidney and prostate cancers." (PMID 31772674, 2019).
Skeletal myopathy (2 papers, 2015 to 2026). "Since 2011, six additional mutations in FHL-1 have been linked to the development of RBM and EDMD, increasing the total number of FHL-1 skeletal myopathy linked mutations from 29 prior to 2011 to 35 after 2011." (PMID 25961035, 2015).
Allergy (1 paper, 2023). An allergy is an immune response or reaction to substances that are usually not harmful. "Interestingly, the anti-inflammatory IL-10 and the allergy-associated cytokines, IL-9 and IL-13, were also significantly lower in FHL1−/− than WT mice at both time points." (PMID 37884534, 2023).
angina pectoris (1 paper, 2022). The symptom of paroxysmal pain consequent to MYOCARDIAL ISCHEMIA usually of distinctive character, location and radiation. "All variants in the credible set of FHL1 were associated with multiple disease endpoints representing major CHD in FinnGen, including angina pectoris and ischemic heart disease." (PMID 35978133, 2022).
Anorexia (1 paper, 2024). Lack of desire to eat (loss of appetite). "Therefore, we cannot exclude a role for FHL1 in the development not only of anorexia in cancer but likely in muscle derangement frequently observed when developing a catabolic status." (PMID 39519555, 2024).
asthma (1 paper, 2022). "Evidence exists reporting that activation of the MAPK pathway is associated with asthma and FHL1 can regulate the MAPK pathway." (PMID 36184652, 2022). "Through the intersection, there was only one gene (FHL1) in the Venn diagram, highlighting FHL1 as an asthma-associated gene." (PMID 36184652, 2022). "Of note, the mechanistic data revealed that FHL1 was targeted by miR-224-5p in asthma, and miR-224-5p was downregulated in lung tissues of asthmatic mouse." (PMID 36184652, 2022). "This intrigued us to clarify the effect of microRNA (miR)-224-5p on biological characteristics of ASMCs in mice with asthma-like airway inflammation and responses through the FHL1-dependent MAPK pathway." (PMID 36184652, 2022). "FHL1 was also found to be abnormally overexpressed in asthma samples in the GSE27066 dataset." (PMID 36184652, 2022). "Moreover, the inner mechanisms of miR-224-5p and FHL1 in clinical tissue samples of asthma and the effect of miR-224-5p on mild or chronic asthma mouse models should be further explored and confirmed in the future." (PMID 36184652, 2022). "miR-224-5p was overexpressed in asthmatic mice to characterize whether the function of miR-224-5p in asthma was achieved by targeting FHL1." (PMID 36184652, 2022). "In addition, an isoform of FHL1, KyoT2, can be considered as a potential target for the treatment of asthma since its overexpression downregulates airway remodeling and resistance in asthmatic mice." (PMID 36184652, 2022). "Hence, we speculated that FHL1 could mediate the MAPK pathway to affect the airway inflammation in asthma." (PMID 36184652, 2022). "Hence, downregulation of FHL1 could block the activation of the MAPK pathway in asthma." (PMID 36184652, 2022). "A heatmap was then plotted based on the expression of top 30 asthma-related DEGs obtained from the GSE6858 dataset, which displayed higher FHL1 expression in the asthma samples than that in the control samples." (PMID 36184652, 2022).
autoimmune disease (1 paper, 2025). A disorder resulting from loss of function or tissue destruction of an organ or multiple organs, arising from humoral or cellular immune responses of the individual to their own tissue constituents. "Sera at the time of diagnosis from patients with IIM (n = 449), autoimmune disease controls (DC, n = 130), neuromuscular diseases (NMDs, n = 16) and healthy controls (HC, n = 100) were analysed for anti-FHL1 autoantibodies by enzyme-linked immunosorbent assay (ELISA)." (PMID 38833674, 2025). "We have previously reported the presence of anti-FHL1 autoantibodies in patients with autoimmune diseases, with higher frequency in patients with IIM." (PMID 38833674, 2025).